SNAI2 (snail family transcriptional repressor 2)
Diseases named in the same sentence as SNAI2 in open-access papers (continued):
Sharing a sentence is not in itself a finding about the gene and the disease.
tumor (continued). "We also explored the expression and distribution of SNAI2 in various tumor tissues and cells by the THPA (Human Protein Atlas) database." (PMID 37251370, 2023). "DEN-treated mice with KLF10 deletion exhibited increased levels of mesenchymal markers (N-cadherin and SNAI2) and tumor metastasis markers (matrix metalloproteinases 2 and 9)." (PMID 37946098, 2023). "In particular, an increased protein level of SNAI2 was observed in EPCAMhigh-cell-derived xenografted tumor tissues than in the EPCAMlow-cell-derived xenografted tumor tissues (p < 0.05)." (PMID 36674577, 2023). "The overexpression of miR-203 inhibits tumor cell invasion by preventing the mesenchymal marker snail family transcriptional repressor 2 (Snail2)." (PMID 37298314, 2023). "SNAI2, occasionally referred to as SLUG, is another member of the Snail transcriptional superfamily that is associated with both embryogenesis and tumor development." (PMID 36980876, 2023). "Nonetheless, our pan-cancer research gives a thorough understanding of SNAI2’s tumor-targeting mechanism." (PMID 37251370, 2023). "SNAI2 exhibited a much higher protein level in SiHa-SNAI2 cell-derived xenografted tumor tissues than in SiHa-Vec cell-derived xenografted tumor tissues (p < 0.05)." (PMID 36674577, 2023). "Given the oncogenic function of SNAI2 in tumor invasion, we analyzed the SNAI2 levels in defined metastasis types." (PMID 34792282, 2022). "As a central EMT-TF and homolog to SNAI1 in the SNAIL transcription factor family, SNAI2 has been documented to play an important role in overcoming apoptosis and mediating drug resistance in tumor cells." (PMID 35864202, 2022). "In turn, ELF3-AS1 downregulation further drives tumor progression by continuously activating SNAI2 signaling and promoting cell proliferation, thereby leading to a poor prognosis in GC." (PMID 36457025, 2022). "In the SU2C cohort, 516 gene sets were exclusively enriched in the high‐SNAI2 group; these gene sets play important roles in tumor invasion and metastasis, such as focal adhesion, hedgehog, MET, PDGFP, and integrin signaling." (PMID 34792282, 2022). "As a classic EMT-TF gene, SNAI2 has recently been shown to be involved in a broader range of biological processes, including tumor metastasis, heart development, cell differentiation, vascular remodeling, and DNA damage repair." (PMID 35529472, 2022). "A xenograft tumor model was constructed in nude mice to further explore the mechanism by which SNAI2 acts to activate the Akt pathway by inhibiting PHLPP2 in vivo." (PMID 35654777, 2022). "SNAI2 also demonstrated an increase in expression correlating with an increasing tumor component in Co5/1 (p = 0.0352)." (PMID 36552039, 2022). "SNAI2 interacts with the tumor microenvironment by regulating reactive stroma and tumor‐infiltrating immune cell profiling." (PMID 34792282, 2022). "The transcription factor, SNAI2 is a notable regulator in various tumor cell biological processes, exerting its influence through transcriptional regulation and contributing to disease progression." (PMID 35654777, 2022). "Extensive research has shown that SNAI2 plays a critical role in melanocytes, adipocytes, and germ cells, contributing to cell differentiation and tumor initiation." (PMID 36726781, 2022). "Accumulating evidence have shown that SNAI2 plays a critical role in driving tumor metastasis by transcriptionally regulating downstream target genes." (PMID 36457025, 2022). "Most of these genes were tumor cell metastasis-associated genes such as TNC, PLAU, PDPN, SPARC, LUM, and especially SNAI2 (Zinc finger protein SLUG transcription factor)." (PMID 35742914, 2022). "The results revealed that compared with oe-NC, the tumor weight and volume were significantly elevated in response to oe-SNAI2, but were decreased following oe-PHLPP2." (PMID 35654777, 2022).
tumor (continued). "For examples, Olmeda and colleagues have confirmed that Snai1 and Snai2 collaborate on tumor growth and metastasis properties of mouse skin cancer cells." (PMID 36457025, 2022). "The oncogenic function of SNAI2 in PC metastasis is well established; e.g., SNAI2 reactivates tumor stroma to facilitate tumor metastasis." (PMID 34792282, 2022). "In nine cohorts of PC patients, SNAI2 expression was significantly decreased in tumor tissue compared with normal prostate tissue, and SNAI2 levels were significantly reduced in primary tumors of higher Gleason grade." (PMID 34792282, 2022). "Recent evidence reveals a broad effect of SNAI2 on cancer progression, including inducing tumor initiation cell, promoting cell invasion and metastasis." (PMID 35220872, 2022). "Our clinical cohort analysis showed relatively higher SNAI2 levels in distant metastatic tissues than in lymph node metastases, suggesting the dynamic changes in SNAI2 expression during tumor progression." (PMID 34792282, 2022). "They elucidated how the epigenetic silencing of SNAI2 controls the dynamic changes in SNAI2 expression that are essential for tumor initiation and progression." (PMID 34792282, 2022). "Next, CIBERSORT was used to assess the correlation between SNAI2 levels and the tumor immune microenvironment." (PMID 34792282, 2022). "The results showed that after treatment with lapatinib for 2 h, the SNAI1 and SNAI2 expression levels in most tumor cell types were decreased, as was their survival ability." (PMID 35898399, 2022). "Though these observations do not align with the EMT role of Snail family members, the authors suggest a tumor suppressor role for SNAI2 that is tumor-type specific." (PMID 35582031, 2021). "This revealed that the stromal co-expression of PEAK1 and SNAI2 was significantly increased in HER2-positive tumor tissues (n = 79)." (PMID 34239043, 2021). "Snai2, which is the most important member of the Snail family, can enhance tumor cell proliferation and invasiveness, whereas Twist1 can mediate EMT during cancer progression, particularly in the acquisition of metastatic potential." (PMID 32661742, 2021). "In recent years, SNAI2 has been shown to be abnormally expressed in various malignant tumors and to play an important role in tumor progression." (PMID 34510400, 2021). "Secondly, FN-RMS cells show the most dependency for SNAI2 compared to all other tumor cell lines, including FP-RMS, in the Broad Achilles CRISPR/Cas9 screen for core dependencies." (PMID 33420019, 2021). "In both tumor types, Snai2 was the most strongly and commonly expressed marker, with higher IHC scores in UC than in UCOGC." (PMID 32661742, 2021). "Similar findings were obtained in a study of therelationship between SNAI2 expression and the overall survivalrate in 10 tumor types." (PMID 33959388, 2021). "Snai2 was the most frequently and strongly expressed marker in both tumor types, in addition to being the most important in determining the observed differences between UC and UCOGC, and a higher mean combined score in UC than in UCOGC (p = 0.03)." (PMID 32661742, 2021). "It is known from other cancers, that FOSL2 is activated by the ERK1/2 kinase leading to the transcription of SNAI2, which plays an important role in tumor metastasis via activation of epithelial-to-mesenchymal transition (EMT)." (PMID 34073664, 2021). "Second, we connect mechanistically the cellular and molecular effects of SNAI2 on blocking tumor differentiation and promoting growth." (PMID 33420019, 2021). "Altogether, these results strongly support a role for SNAI2 on tumor growth and as a potent suppressor of myogenic differentiation in FN-RMS." (PMID 33420019, 2021). "Snai2 was the most frequently and strongly expressed marker in both tumor types (10/10 UC, 8/16 UCOGC), and its expression was higher in UC than in UCOGC (mean immunohistochemical score: 4.8 in UC vs. 2.1 in UCOGC, p < 0.01)." (PMID 32661742, 2021).
tumor (continued). "Due to the importance of RAS as an oncogenic driver in FN-RMS, we sought to evaluate if the effects of SNAI2 on differentiation, in the same tumor context, involved the RAF-MEK-ERK pathway." (PMID 33420019, 2021). "The regulation of tumor metastasis by SNAI2 is not only limited to epithelial-derived carcinomas but also interstitial tumors." (PMID 31749661, 2019). "In malignant tumors of epithelial origin, SNAI2 promotes tumor cell metastasis through epithelial–mesenchymal transition (EMT)." (PMID 31749661, 2019). "We also demonstrated the co-operative function of RUNX1 and FOSL2 in maintaining the expression of SNAI2, a key mediator of epithelial–mesenchymal transition and tumor dissemination." (PMID 30903020, 2019). "Co-staining for SNAI2 showed that SNAI2 was predominantly expressed in the stromal section of the normal-appearing mucosa and tumor section of mice after AOM/DSS treatment and was absent from epithelial compartment." (PMID 32566755, 2019). "SNAI2 is a prominent EMT-inducing transcription factor that facilitates tumor cell invasion, metastasis, and survival." (PMID 31749661, 2019). "Acquisition of mesenchymal properties by tumor cells is associated with an upregulation of EMT transcriptional inducers such as TWIST1/2, SNAI2/SLUG, and ZEB1." (PMID 31075939, 2019). "The relationship between grade and SNAI2 methylation in tumour tissue was confirmed by multivariate logistic regression analysis." (PMID 30189837, 2018). "Among the cancer-specific methylated genes, we found lower methylation levels of the SNAI2 gene in histologic grade 3 tumours (OR = 0.61; 95% CI, 0.39–0.97; P = 0.038) than in fully or moderately differentiated cancers." (PMID 30189837, 2018). "High levels of SNAI2 in ER+ metastatic tumor samples from two cohorts of patients treated with endocrine therapy in the advanced setting correlated significantly with poor clinical outcome." (PMID 29921289, 2018). "In the present study, we investigated promoter methylation in six genes associated with tumour invasivity (ADAM23, uPA, CXCL12, TWIST1, SNAI1 and SNAI2)." (PMID 30189837, 2018). "We previously showed that miR-203 inhibits tumor growth by directly targeting transcription factor Snai2." (PMID 30241553, 2018). "Disruption of SNAI2 can sensitize the tumor cells to apoptosis signaling and delay the development of mammary gland." (PMID 28407751, 2017). "SNAI2 transforms normal fibroblasts to an aggressive form and boost their tumor–supporting role in 3D organotypic culture and OC murine xenograft model." (PMID 29041931, 2017). "In this setting, our analysis showed that SNAI2 was elevated specifically in the tumor stroma along OC progression and was capable of transforming normal fibroblasts into CAFs." (PMID 29041931, 2017). "To exclude the possibility that the SNAI2 correlated gene set represents the immune cells in the tumor microenvironment, we performed data mining and revealed that the gene set was highly represented in fibroblasts but not in hematopoietic cell lineages." (PMID 29041931, 2017). "Taken together, our data showed here that SNAI2 expression supported the emergence of a CAF-like cell state, impacted tumor matrix stiffness and in turn regulated fibroblast SNAI2 expression and its subsequent activation." (PMID 29041931, 2017). "SNAI2 and its regulated signature were particularly expressed in the desmoplasia subtype of OC, discriminated tumor stroma from their normal counterpart, stratified stroma activation and affected patient outcome." (PMID 29041931, 2017). "In this study, we demonstrated that SNAI2 was advantageously expressed in stromal fibroblasts and correlated with tumor stromal activation and a worse OC patient prognosis." (PMID 29041931, 2017). "SNAI2 drove a transcriptional signature in the mesenchymal subtype of OC that contributed to tumor desmoplasia, which fed back to increase SNAI2 expression and sustain fibroblast activation." (PMID 29041931, 2017).
tumor (continued). "In tumor microenvironment, fibroblasts were demonstrated to be the major residents that express SNAI2." (PMID 29041931, 2017). "Ultimately, SNAI2 silencing in activated fibroblast diminished their role in supporting tumor cell growth in 3D organotypic coculture model." (PMID 29041931, 2017). "To explore the expression pattern of SNAI2 in epithelial OC, we analyzed a microdissected profile of OC and found that SNAI2 was decreased in the tumor epithelium and was elevated in the tumor stroma, compared with their normal counterparts." (PMID 29041931, 2017). "In conclusion, this study established a role for stromal SNAI2 that is distinct but highly complementary to its established role in regulating EMT in OC tumor cells." (PMID 29041931, 2017). "In this study, we extended the study of SNAI2 from tumor cells to stromal fibroblasts and discovered that SNAI2 and its associated mesenchymal signature were enriched in the desmoplasia subtype of OC." (PMID 29041931, 2017). "Our results address the role of SNAI2 in reprogramming OC stromal fibroblasts and the facilitation of tumor progression." (PMID 29041931, 2017). "SNAI2 expression alteration influence of tumor growth in primary CAFs was evaluated in 3D organotypic and murine xenograft models." (PMID 29041931, 2017). "The elevation of SNAI2 in stromal cells along tumor progression was validated in microdissected breast profiles." (PMID 29041931, 2017). "These preliminary findings concerning SNAI2 in OC tumor stroma is completing our recognition of the role of SNAI2 in OC." (PMID 29041931, 2017). "We demonstrated that SNAI2 was frequently activated in the tumor stroma, correlated with fibroblast activation and worse patient outcome in OC." (PMID 29041931, 2017). "Herein, we surprisingly identify that anchorage-independent growth, including the formation of tumor sphere and soft agar colony, is significantly increased when SNAI2 expression is inhibited by shRNAs in HCC cells." (PMID 27760172, 2016). "Our results implicate that SNAI2 behaves as a tumor suppressor by inhibiting multidrug resistance via suppressing ABC transporter genes in HCC cells." (PMID 27760172, 2016). "It is intriguingly to notice that over-expression of SNAI2 effectively inhibited the tumor sphere formation of SMMC-7721 cells, which is consistent with previous results." (PMID 27760172, 2016). "When tumor progressed to high-grade carcinomas, SNAI2-expressing cells remain to local instead of detaching and metastasis." (PMID 27760172, 2016). "Our present results suggest that miR-203 serves as a tumor suppressor, whereby AR activates miR-203, and the induction of miR-203 reduces SNAI2 levels." (PMID 27028864, 2016). "Studies performed in cell and human tumor xenograft models of PCa have revealed that SNAI2 promotes cell migration and invasion and is a critical mediator of Cyclin D1b–induced oncogenic activity." (PMID 25686823, 2015). "The current understanding of the EMT process is that transcription factors including SNAI1, SNAI2, ZEB1, ZEB2 and TWIST1 down-regulate CDH1 expression which subsequently results in the loss of cell adhesion and migration of tumor cells." (PMID 26214683, 2015). "SNAI2 expression is suggested to maintain the pool of cancer stem cells, allowing tumor cells to leave the primary tumor, colonize ectopic tissues, and induce therapy resistance." (PMID 25797249, 2015). "CDH1 transcriptional repressors, such as SNAI1 (SNAIL), SNAI2 (SLUG), ZEB1, ZEB2 (SIP1), E12/E47, and TWIST have traditionally been implicated in promoting EMT in various systems of embryonic development and tumor progression." (PMID 24968068, 2014). "The function of the Snai1 and Snai2 genes have been studied extensively during both vertebrate embryogenesis and tumor progression and metastasis, and play critically important roles during these processes." (PMID 23762348, 2013).
tumor (continued). "SNAI2, also known as SLUG, is an important functional suppressor of human breast progenitor cell lineage commitment and differentiation, promoting normal and tumor mammary gland stem/progenitor cells state." (PMID 24260469, 2013). "Many of the EMT-inducing transcription factors such as SNAI1 (SNAIL), SNAI2 (SLUG), ZEB1, ZEB2, TWIST1, FOXC2 and Goosecoid have been associated with tumor invasion and metastasis." (PMID 24040120, 2013). "The gain of mesenchymal cell markers such as Vimentin (VIM), Snail homolog 2 (SNAI2), and fibronectin (FN) has been observed in tumor progression." (PMID 23717581, 2013). "Both Smad and ERK pathways are involved in up-regulating the expression of SNAI2 which positively controls α3β1-mediated migration of tumor cells." (PMID 24260309, 2013). "With regard to this issue, overtly blunted tumor growth rate was found in MDA-MB-231 SNAI2-shRNA cells." (PMID 24260469, 2013). "SNAI2 has a positive effect on α3β1-mediated invasiveness of tumor cells, since SNAI2 promotes the production of MMP-2 and MMP-9." (PMID 24260309, 2013). "Once in the nucleus, MUC1 acts as a co-activator for the expression of genes linked to tumor cell invasion and metastasis including the EMT-promoting genes TWIST1, SNAI1 and SNAI2." (PMID 22586492, 2012). "We observed that EGF induced nuclear localization of the MUC1 cytoplasmic domain leading to expression of genes linked to tumor cell invasion and metastasis including TWIST1, SNAI1 and SNAI2." (PMID 22586492, 2012). "Down-regulation of E-cadherin, occludin, claudin 3, 4, 7 as well as up-regulation of the mesenchymal genes and SNAI2 is in line with the features described in claudin-low tumor samples." (PMID 22044755, 2011). "Taken together, these data indicate that SNAI2/Slug is overexpressed in a subpopulation of human gliomas, and its expression correlates with invasive phenotype and tumor grade." (PMID 20565806, 2010). "Using this approach, we identified HIF1A, STAT3 and SNAI2 (Slug) as the three most overexpressed migration-related transcription factors in human glioblastomas when compared to non-tumor brain." (PMID 20565806, 2010). "However, it was only in the originating tumor tissue that SNAI2+ tumor cells displayed signs of EMT, shown by reduced E‐cadherin/CDH1 expression, which was largely restricted to cells at the tumor–stroma interface." (PMID 40600748, 2025). "In addition to RAS pathway activation, TPM cancer cells display significantly elevated SNAI2 expression compared to wild-type (WT) cancers across a range of tumor types." (PMID 40560846, 2025). "SNAI1 and SNAI2 are key regulators of tumor metastasis and drug resistance." (PMID 39708716, 2025). "Except for SNAI2, all markers were significantly expressed in tumor cells." (PMID 39935174, 2025). "Interestingly, only PPARD expression positively correlated with an EMT-related gene signature formed by ZEB1, SNAI1, and SNAI2 in the tumor." (PMID 40607925, 2025). "High levels of SNAI2 have been found to accelerate tumor progression, but its function in VM formation remains unclear." (PMID 38702792, 2024). "The results showed a significant reduction in tumor volume after SNAI2 downregulation." (PMID 38702792, 2024). "Indeed, it has been recently reported that circulating tumor cell migration is also promoted through a fibronectin-dependent mechanism that modulates the activity of the transcription factor SNAI2." (PMID 37511550, 2023). "Additionally, lower EPCAM, β-catenin, β-catenin (in the nucleus), c-Myc, and SOX2 protein levels were seen in SiHa-SNAI2-cell-derived xenografted tumor tissues compared to SiHa-Vec-cell-derived xenografted tumor tissues (p < 0.05)." (PMID 36674577, 2023). "Additionally, the protein levels of SNAI2, EPCAM, β-catenin, c-Myc, and SOX2 were detected in xenografted tumor samples formed by SiHa-Vec and SiHa-SNAI2 cells." (PMID 36674577, 2023). "SNAI2 was expressed differently in different human tissues and tumor cell lines." (PMID 37251370, 2023).